LINC01638 (long independently transcribed non-coding RNA 1638)
Synonyms: lncRNA4114
Gene: Long non-coding RNA gene on chromosome 22 (27,159,861 to 27,225,134, reverse strand). Ensembl gene ENSG00000233521.
Diseases named in the same sentence as LINC01638 in open-access papers:
LINC01638 is named in the same sentence as 13 diseases in open-access papers, as found by Europe PMC text mining. Sharing a sentence is not in itself a finding about the gene and the disease. The quoted sentences say what the papers report.
pancreatic ductal adenocarcinoma (2 papers, 2021 to 2023). An infiltrating adenocarcinoma that arises from the epithelial cells of the pancreas. "Induced overexpression of LINC01638 in pancreatic ductal adenocarcinoma promoted cell migration and invasion through epithelial-to-mesenchymal transition (EMT)-like mechanisms." (PMID 37985890, 2023). "LINC01638 has been reported to be involved in the progression of several cancers, such as pancreatic ductal adenocarcinoma, non-small cell lung cancer, breast cancer and colorectal adenocarcinoma." (PMID 33714208, 2021). "Recently, some references indicated that LINC01638 positively regulates the development of prostate carcinoma, lung cancer and pancreatic ductal adenocarcinoma." (PMID 33714208, 2021).
papillary thyroid carcinoma (2 papers, 2021 to 2023). "To explore the role of ELK1 and LINC01638 in papillary thyroid carcinoma, we firstly looked at their expression in TPC-1, IHH-4, BCPAP and Nthy-ori 3–1." (PMID 34281460, 2021). "In addition, LINC01638 expression in papillary thyroid carcinoma cells has been demonstrated to regulate cell proliferation via interactions and modulation of the Wnt/beta-catenin pathway and activation of Axin253." (PMID 37985890, 2023).
triple-negative breast carcinoma (2 papers, 2021 to 2022). An invasive breast carcinoma which is negative for expression of estrogen receptor (ER), progesterone receptor (PR), and human epidermal growth factor receptor 2 (HER2). "Studies showed that LINC01638 was highly expressed in triple-negative breast cancer (TNBC) tissues and LINC01638 mediated TNBC progression by interacting with c-Myc and activating MTDH-Twist1 signaling." (PMID 34281460, 2021).
breast carcinoma (1 paper, 2021). "For instance, LINC01638 is firstly found to promote breast cancer progression through activating MTDH-Twist1 signaling." (PMID 33714208, 2021).
lymph node metastasis (1 paper, 2021). "Furthermore, LINC01638 expression was positively correlated with clinical stage and lymph node metastasis." (PMID 33714208, 2021).
sarcoma (1 paper, 2023). A usually aggressive malignant neoplasm of the soft tissue or bone. "Additionally, LINC01638 expression is elevated in several cancer types and is specifically elevated in mesenchymal-derived sarcomas compared to normal control tissue." (PMID 37985890, 2023).
cancer (4 papers, 2021 to 2023). A tumor composed of atypical neoplastic, often pleomorphic cells that invade other tissues. "LINC01638 was identified to be associated with human cancers as an oncogene." (PMID 33714208, 2021). "Inhibition of LINC01638 reduces tumor growth in cancers, including prostate and breast, both of which metastasize to bone." (PMID 37985890, 2023). "Further, our ChIRP studies reveal chromatin-associated genes that contribute to the stabilization and reorganization of chromatin interactions by LINC01638 that may be important in cancer cell survival and progression." (PMID 37985890, 2023). "LncRNA LINC01638 is reportedly a critical oncogene in the development of certain cancers." (PMID 34281460, 2021). "We focused on LINC01638, which is highly expressed in hMSCs and has been studied in cancers, but not in regulating osteogenesis." (PMID 37693373, 2023).
tumor (3 papers, 2021 to 2023). "In TNBC, multiple lncRNAs had been identified to regulate EMT pathways and tumor invasion via interacting with various molecules, such as LINC01638, GAS5, UCA1, ARNILA, and NNT-AS1." (PMID 34873403, 2021).
LINC01638 also shares sentences with these, for which no sentence is quoted: colorectal adenocarcinoma (1 paper); hepatocellular carcinoma (1); lung carcinoma (1); melanoma (1); prostate carcinoma (1).